ABCC2 (ATP binding cassette subfamily C member 2)
Diseases named in the same sentence as ABCC2 in open-access papers (continued):
Sharing a sentence is not in itself a finding about the gene and the disease.
ABCC2 also shares sentences with these, for which no sentence is quoted: head and neck squamous cell carcinoma (4 papers); steatosis (4); Crigler-Najjar syndrome (3); esophageal squamous cell carcinoma (3); Gilbert syndrome (2); leukemia (2); nasopharyngeal carcinoma (2); progressive familial intrahepatic cholestasis (2); small cell lung carcinoma (2); Tangier disease (2); type 1 diabetes mellitus (2); -immune diseases (1); acute liver failure (1); adrenoleukodystrophy (1); age (1); Alagille syndrome (1); alcohol cirrhosis (1); Alzheimer disease (1); amyotrophic lateral sclerosis (1); Anxiety (1); autosomal recessive congenital ichthyosis 4B (1); benign tumors (1); cardiomyopathy (1); cholangiocarcinoma (1); chronic kidney disease (1); colon adenoma (1); congenital heart disease (1); cyst (1); cystic fibrosis (1); Diarrhea (1).
A further 47 diseases each share a sentence with ABCC2 in 1 paper.